Y_RNA (Y RNA )
Gene: Miscellaneous RNA gene on chromosome 7 (37,435,115 to 37,435,216, forward strand). Ensembl gene ENSG00000201566.
Homologues: Orthologues: chimpanzee Y_RNA (100% identical), macaque Y_RNA (86% identical). Paralogues in human: RNY3 (89% identical), Y_RNA (89% identical), Y_RNA (87% identical), RNY3P1 (86% identical), Y_RNA (86% identical), Y_RNA (85% identical), RNY3P14 (84% identical), Y_RNA (84% identical), RNY3P16 (83% identical), Y_RNA (83% identical), Y_RNA (82% identical), RNY3P11 (81% identical), and 94 more.